LTBR (lymphotoxin beta receptor)
Diseases named in the same sentence as LTBR in open-access papers (continued):
Sharing a sentence is not in itself a finding about the gene and the disease.
infection (continued). "We challenged LTβR+/+ and LTβR−/− cells with the PEDV CV777 strain (at a multiplicity of infection (MOI) of 1), and cells were harvested 48 h later to determine the relative viral expression level by real-time PCR using PEDV-specific primers." (PMID 30469426, 2018). "In infection models with L. monocytogenes and M. tuberculosis, LTβR−/− mice not only show a delayed/abrogated activation of the innate immune response but also an absence of specific T cell responses." (PMID 28845089, 2017). "Overall these data reveal a crucial role for LTβR expression by FRCs in promoting infection-induced lymphangiogenesis and DCs accumulation in the mLN." (PMID 28848229, 2017). "It has been demonstrated that the LTβR plays a role in controlling infections with intracellular pathogens such as M. tuberculosis and L. monocytogenes." (PMID 28845089, 2017). "Expression levels for IL-12p40 decreased in WT animals by day 7 p.i, whereas LTβR−/− animals showed much lower expression levels compared to WT animals before infection, but a transient increase in IL-12p40 expression on day 14 p.i.." (PMID 28845089, 2017). "Next, we biochemically analyzed NF-κB activation in IECs derived from WT mice intraperitoneally injected with antagonistic LTβR-Ig or a control-Ig 1 day prior to oral infection with C. rodentium." (PMID 25905673, 2015). "Disruption of LTβR signal using LTβR-Ig fusion protein was shown to compromise innate immune responses upon subsequent infection with C. rodentium, a natural mouse enteric pathogen that led to mortality." (PMID 25905673, 2015). "A single dose (100 μg) of anti-LTβR mAb at the time of infection was sufficient to reduce hepatic parasite burden as early as day 7 p.i.." (PMID 21998581, 2011). "Notably, ILC3 production of LT has been described in the intestine during Citrobacter rodentium infection, and LTβR signaling in intestinal epithelial cells was required for recruitment of neutrophils to the infection site via production of CXCL1 and CXCL2." (PMID 35845169, 2022). "Similarly, the absolute numbers of NK1.1+CD3+ NKT cells in WT mice declined during the course of infection but were higher than those of LTβR−/− mice before infection and on days 4 and 7 p.i., which is in accordance with published data." (PMID 33753412, 2021). "Dysregulated cytokines in the serum of LTβR−/− mice after infection with T. gondii." (PMID 33753412, 2021). "All these observations revealed the function of LTβR in infection." (PMID 30469426, 2018). "In addition to the critical role of LTβR in protection against infection, the involvement of LTβR in the regulation of the microbial community composition has been reported." (PMID 30469426, 2018). "Differentiation of helper T cells is controlled by the LTβR mediated signaling but may differ under specific infections or diseases." (PMID 30531962, 2018). "Interestingly, LTβR−/− mice survived the acute phase of infection and only started succumbing to the infection in the early chronic phase on day 19 with an overall survival of 30%." (PMID 28845089, 2017). "In addition to these small infiltrates, LTβR−/− lungs showed large inflammatory infiltrates on days 7 and 21 after infection." (PMID 28845089, 2017). "Notably, control animals died at about 10 days post infection (p.i.), while LTβR-Ig treatment significantly (P = 0.0098) extended the survival of infected mice to about day 20 p.i." (PMID 25993659, 2015). "Finally, we have identified two different mAbs that target LTβR with distinct functional outcomes on anti-parasitic immunity at different stages of infection." (PMID 21998581, 2011). "Thus, treatment of L. donovani-infected mice with two different anti-LTβR mAbs had distinct effects on the course of infection, reflecting different functional properties of these mAbs." (PMID 21998581, 2011). "Therefore, the data suggest that disruption of LTαβ – LTβR signaling prevents microvascular pathology induced by PbA blood stage infection." (PMID 18612394, 2008).
infection (continued). "However, 90% of iLTβRΔ/Δ mice survived infection, compared to 100% mortality in LTβR-/- mice." (PMID 34335629, 2021). "For example, LTβR−/− mice are sensitive to bacterial infection due to the absence of lymphoid organs in these mice, and LTβR signaling in intestinal epithelial cells is required for the recruitment of neutrophils to the site of infection during early infection via the production of CXCL1 and CXCL2." (PMID 30469426, 2018). "TNFRSF14 and LTβR, the 2 competitive TNFSF14 receptors, followed distinct kinetics in terms of transcriptional regulation and protein expression in TR-AMs during the infection course." (PMID 41252214, 2026). "The requirement for LTβR signaling in initiating the innate IFN-I response was demonstrated in human and mouse infection models with CMV and other viral pathogens." (PMID 35604387, 2022). "The host–pathogen infection models demonstrate unique and shared ligands and bidirectional pathways of the HVEM and LTβR pathways." (PMID 35604387, 2022). "After infection with 40 cysts of T. gondii ME49, LTβR−/− mice started to succumb to infection by day 12 and overall survival was 9.1%." (PMID 28845089, 2017). "gondii infection, demonstrating perturbed B-cell and T-cell subpopulations in the absence of LTβR signaling." (PMID 40924438, 2025). "The gene expression of the LTβ receptor, Ltβr, was stable during LuCAdV5 infection and no statistically significant changes in expression were observed during the stages of infection-induced inflammation." (PMID 39355243, 2024). "This coincided with a 4–5-fold increase of neutrophils in the lung tissue 18 h post infection, which was mildly elevated in the absence of LTβR." (PMID 33568785, 2021). "Since LTβR−/− mice are known to have fewer NK cells and NKT cells, it was not surprising to observe that absolute NK1.1+ cells were significantly higher in WT than in LTβR−/− mice before infection and on days 4 and 7 p.i.." (PMID 33753412, 2021). "The overexpression of LTβR, or the activation of its mediated signaling by its functional antibody or cellular receptors such as LIGHT, will also be needed to positively determine its role in preventing infection." (PMID 30469426, 2018). "On the other hand, expression of induced nitric oxide synthase (iNOS) was much lower in LTβR−/− animals compared to WT animals before infection and did not increase markedly after infection." (PMID 28845089, 2017). "The anti-LTβR 3C8 enhanced parasite clearance in the liver during an established infection, but had no anti-parasitic effect in the first 14 days of infection (data not shown), unlike the anti-LTβR mAb LLBT2." (PMID 21998581, 2011). "The expression of LTBR in PBMC from both animal groups generally decreased after 21 dpi; interestingly, however, a modest increase (1.4-fold, P = 0.0510) was detected at 14 dpi relative to pre-infection in the N'Dama group." (PMID 19409086, 2009). "Instead, LIGHT may send inhibitory signals via LTβR early during infection, although no such LTβR-mediated negative signalling pathway has yet been defined." (PMID 21998581, 2011). "The anti-parasitic effects of anti-LTβR mAb (LLTB2) were observed when it was administered at the time of infection, but not in mice with an established L. donovani infection, suggesting that a mAb with similar functional characteristics would have limited therapeutic potential for treatment of VL." (PMID 21998581, 2011). "Interestingly, although slightly higher amounts of IFNγ could be found in LTβR−/− compared to WT animals before infection, these amounts did not increase after infection, as seen in WT animals, where levels rose about 4-fold." (PMID 28845089, 2017). "In line with published data, we found a virtual absence of NK1.1+ cells in LTβR−/− mice, and NK1.1+ cell numbers dropped in WT mice after infection, probably due to conversion into ILCs." (PMID 33753412, 2021).
infection (continued). "LTβR−/− animals did not exhibit such a distinct increase p.i.; GTPBP1 expression levels were only moderately increased during the course of infection." (PMID 28845089, 2017). "Therefore, disruption of LTβR signaling while protecting from ECM development, had no strong effect on the typical hematological / inflammatory response to PbA infection in mice." (PMID 18612394, 2008). "In conclusion, LTβR−/− compared to WT mice do not show a significant difference in overall and antigen-specific T cell numbers either before or after T. gondii infection, but B cell, NK1.1+, and NKT cell numbers appear to be significantly affected by the absence of LTβR before and during infection." (PMID 33753412, 2021).
bacterial infection (4 papers, 2015 to 2021). "To define the role of LTβR signaling in generation of specific IgA in response to mucosal bacterial infection, we infected iLTβRΔ/Δ mice with C. rodentium." (PMID 34335629, 2021). "Several reports have demonstrated the critical role of LTβR signaling in bacterial infection of intestinal epithelial cells." (PMID 30469426, 2018). "Although, a defect in the colonic patches in Nfkb2−/− mice could impair IL-22 mediated protective responses, our cell-intrinsic crosstalk model explained that the reported epithelial requirement of LTβR is in sustaining RelA NF-κB response during bacterial infection." (PMID 25905673, 2015).
adenocarcinoma (1 paper, 2019). A common cancer characterized by the presence of malignant glandular cells. "CD40 gene overexpression was correlated with improved five-year overall survival (OS) (p < 0.001), while increased BAFFR and LTβR mRNA levels were associated with worse OS in patients with adenocarcinomas (p < 0.001 and p < 0.001, respectively)." (PMID 31137630, 2019). "A positive association with OS also emerged for LTβR gene expression in patients with adenocarcinomas." (PMID 31137630, 2019). "With regard to LTβR expression, patients with adenocarcinomas and high LTβR expression had poor clinical outcome after a five-year observation period (p < 0.001)." (PMID 31137630, 2019).
immunodeficiency (1 paper, 2025). Failure of the immune system to protect the body adequately from infection, due to the absence or insufficiency of some component process or substance. "While LTβR-deficient patients generally fare well with IVIG replacement therapy, NIK-deficient patients exhibit severe, life-threatening combined immunodeficiency with increased susceptibility to bacterial, viral, and protozoan infections, often necessitating HSCT as a life-saving intervention." (PMID 41280889, 2025).
lung (1 paper, 2019). "Moreover, the observed overexpression of NF-κΒ2 in NSCLC is consistent with the overexpression of the TNF receptor family member, LTβR (lymphotoxin-β receptor), that occurs in 87 to 96% of a wide range of solid tumors, including lung cancert." (PMID 31586084, 2019).
neurodegenerative disease (1 paper, 2018). A disorder of the central nervous system characterized by gradual and progressive loss of neural tissue and neurologic function. "LTβR may become a potential therapeutic target in the future in treating various neurodevelopmental and neurodegenerative diseases." (PMID 29463313, 2018).
LTBR also shares sentences with these, for which no sentence is quoted: pancreatic cancer (5 papers); COVID-19 (3); gastric cancer (3); infectious disease (3); prostate carcinoma (3); Glucose intolerance (2); hepatitis B (2); parasite infections (2); renal cell carcinoma (2); type 1 diabetes (2); Allergy (1); Alzheimer disease (1); amyotrophic lateral sclerosis (1); Ataxia (1); autoimmune hepatitis (1); autoimmune pancreatitis (1); biliary tract cancer (1); blood cancers (1); cervical cancer (1); colon adenocarcinoma (1); cutaneous leishmaniasis (1); dementia (1); diffuse large B-cell lymphoma (1); dry eye (1); follicular lymphoma (1); head and neck squamous cell carcinoma (1); idiopathic pulmonary fibrosis (1); IgA nephropathy (1); Insulin resistance (1); intrahepatic cholangiocarcinoma (1).
A further 25 diseases each share a sentence with LTBR in 1 paper.